SPATA31E1 (SPATA31 subfamily E member 1)
Description:
May play a role in spermatogenesis.
Synonyms: C9orf79; FAM75E1; FLJ35866
Tractability: Antibody: UniProt predicts a signal peptide or a membrane-spanning region.
Gene: Protein-coding gene on chromosome 9 (87,882,877 to 87,888,903, forward strand). Ensembl gene ENSG00000177992.
Subcellular location: Membrane
Gene Ontology:
Cellular component: membrane
Genetic constraint (gnomAD): Loss-of-function variants: 7 observed, 12.06 expected, observed/expected ratio (o/e) 0.58, 90% interval 0.33 to 1.09. The upper end of that interval is the gene's LOEUF score, 1.09, which puts it in group 4 of 6, group 1 being the genes least tolerant of losing a copy. Missense variants: 1,961 observed, 1,866.1 expected, observed/expected ratio (o/e) 1.05, 90% interval 1.01 to 1.09. Synonymous variants: 771 observed, 750.23 expected, observed/expected ratio (o/e) 1.03, 90% interval 0.97 to 1.09.
Homologues: Orthologues: chimpanzee SPATA31E1 (98% identical), rat Spata31 (18% identical), mouse Spata31 (18% identical). Paralogues in human: SPATA31A6 (32% identical), SPATA31A1 (31% identical), SPATA31A3 (31% identical), SPATA31A5 (31% identical), SPATA31A7 (31% identical), SPATA31C1 (28% identical), SPATA31C2 (27% identical), SPATA31D1 (24% identical), SPATA31F1 (14% identical), SPATA31D3 (14% identical), SPATA31D4 (14% identical), SPATA31F3 (2% identical).
Diseases named in the same sentence as SPATA31E1 in open-access papers:
SPATA31E1 is named in the same sentence as 2 diseases in open-access papers, as found by Europe PMC text mining. Sharing a sentence is not in itself a finding about the gene and the disease. The quoted sentences say what the papers report.
male infertility (1 paper, 2016). The inability of the male to effect fertilization of an ovum after a specified period of unprotected intercourse. "Validation of class II high-impact variants within SPATA31E1, OVGP1, FOXP1, FBXO43 indicate further putative loci for stallion fertility, however the consequences of mutations on male infertility in human and mice are not yet known." (PMID 27079378, 2016).
SPATA31E1 also shares sentences with these, for which no sentence is quoted: infertile (1 paper).